Y_RNA (Y RNA )
Gene: Miscellaneous RNA gene on chromosome 6 (99,526,097 to 99,526,205, forward strand). Ensembl gene ENSG00000274603.
Homologues: Orthologues: chimpanzee Y_RNA (99% identical), macaque Y_RNA (95% identical). Paralogues in human: RNY1 (94% identical), Y_RNA (91% identical), Y_RNA (90% identical), RNY1P8 (89% identical), Y_RNA (89% identical), RNY1P11 (88% identical), RNY1P7 (88% identical), Y_RNA (88% identical), Y_RNA (87% identical), Y_RNA (86% identical), Y_RNA (85% identical), RNY1P10 (84% identical), and 99 more.